NPB (neuropeptide B)
Description:
May be involved in the regulation of feeding, neuroendocrine system, memory, learning and in the afferent pain pathway.
Synonyms: PPL7; PPNPB; L7
Tractability: Antibody: its Gene Ontology location is reachable by antibodies, with high confidence; UniProt places it where antibodies can reach, with medium confidence; UniProt predicts a signal peptide or a membrane-spanning region.
Gene: Protein-coding gene on chromosome 17 (81,900,745 to 81,902,905, forward strand). Ensembl gene ENSG00000183979.
Subcellular location: Secreted
Pathways (Reactome):
Signal Transduction: G alpha (i) signalling events; Peptide ligand-binding receptors
Gene Ontology:
Molecular function: protein binding; G protein-coupled receptor binding
Biological process: G protein-coupled receptor signaling pathway; feeding behavior
Cellular component: extracellular region
Genetic constraint (gnomAD): Loss-of-function variants: 8 observed, 5.08 expected, observed/expected ratio (o/e) 1.58, 90% interval 0.86 to 1.94. That is too few expected variants to judge how well the gene tolerates losing a copy. Missense variants: 199 observed, 138.68 expected, observed/expected ratio (o/e) 1.43, 90% interval 1.28 to 1.61. Synonymous variants: 118 observed, 75.42 expected, observed/expected ratio (o/e) 1.56, 90% interval 1.35 to 1.82.
Homologues: Orthologues: chimpanzee NPB (98% identical), macaque NPB (92% identical), dog NPB (71% identical), pig NPB (70% identical), mouse Npb (56% identical), rat Npb (49% identical), tropical clawed frog npb (47% identical), zebrafish npb (47% identical). Paralogues in human: NPW (33% identical).
Diseases named in the same sentence as NPB in open-access papers:
NPB is named in the same sentence as 14 diseases in open-access papers, as found by Europe PMC text mining. Sharing a sentence is not in itself a finding about the gene and the disease. The quoted sentences say what the papers report.
Obesity (6 papers, 2013 to 2021). Accumulation of substantial excess body fat. "Animal studies showed that mice with depleted NPBW1 (NPBW1-/-) and neuropeptide B-deficient mice (NPB-/-) develop mild adult onset obesity." (PMID 34067710, 2021). "Nevertheless, as we already mentioned, NPB or NPBWR1‐deficient mice have features consistent with adult‐onset obesity as well as impaired energy expenditure, which is a hallmark of brown fat tissue deficiency." (PMID 33629519, 2021). "Consistently, male NPB ‐deficient mice (NPB −/−) developed adult‐onset obesity." (PMID 33629519, 2021). "NPBWR is a receptor for the neuropeptide W and neuropeptide B. Ablation of this receptor in mice leads to obesity, and NPBWR signaling has a role in the central regulation of energy balance." (PMID 34572017, 2021). "NPB involvement in the maintenance of body weight was demonstrated on NPB gene knockout mice with late onset of obesity." (PMID 30087623, 2018). "Both Npb−/− and Npbwr1−/− mice show late-onset obesity and hyperphagia, suggesting that the endogenous NPB-NPBWR1 pathway negatively regulates feeding behavior and positively regulates energy expenditure." (PMID 23515889, 2013).
Anorexia (1 paper, 2021). Lack of desire to eat (loss of appetite). "The downregulation of circulating NPB levels in patients with anorexia was independently confirmed by a study of 30 healthy controls and 30 patients with AN." (PMID 34205710, 2021). "Nevertheless, as pointed out in this work, NPB levels were evaluated in only 30 healthy controls and 46 patients with anorexia; therefore, these results should be interpreted cautiously." (PMID 34205710, 2021).
anorexia nervosa (1 paper, 2018). A disorder most often seen in adolescent females characterized by a refusal to maintain a minimally normal body weight, an intense fear of gaining weight, a disturbance in body image, and, in postmenarcheal females, the development of amenorrhea. "In detailed diagnostics of anorexia nervosa (especially in the cases of the extreme form of this disorder) it is worth considering testing neuropeptide B and vaspin levels in serum." (PMID 29984256, 2018). "The aim of the study was to assess the correlation between the levels of neuropeptide B, neuropeptide W, vaspin, and the total antioxidant status in the blood, as well as nutritional status of patients with anorexia nervosa." (PMID 29984256, 2018). "Adjusted serum neuropeptide B level according to Body Mass compared to parallel adjusted serum vaspin and TAS levels proved to be a significant predictor for extreme anorexia nervosa (according to ROC curves)." (PMID 29984256, 2018). "The aim of the study was to assess the correlation between the levels of neuropeptide B (NPB), neuropeptide W (NPW), vaspin (VAS), and the total antioxidant status (TAS) in the blood, as well as nutritional status of patients with anorexia nervosa (AN)." (PMID 29984256, 2018).
dementia (1 paper, 2025). Loss of intellectual abilities interfering with an individual's social and occupational functions. "However, the trend of elevated serum levels of anti-NPB antibody in dementia was observed in both sex." (PMID 40406128, 2025). "Considering the expression of NPB and ADGRF5 in the central nervous system, these findings suggest that autoantibodies targeting NPB or ADGRF5 may contribute to the pathogenesis of dementia." (PMID 40406128, 2025).
diabetes (1 paper, 2022). "The aim of the study is to investigate the impact of diabetes on the neuropeptide B/W signaling system in different heart compartments and neurons which innervates it." (PMID 36499546, 2022).
infection (3 papers, 2022 to 2024). The state of being infected such as from the introduction of a foreign agent such as serum, vaccine, antigenic substance or organism. "The pathogen infection stage at 36 hpi in the lsiR76113 knock-down lines also lagged substantially behind that of NPB." (PMID 37949839, 2024).
cancer (1 paper, 2022). A tumor composed of atypical neoplastic, often pleomorphic cells that invade other tissues. "Moreover, high expression of 53BP1 in metastasized cancer cells may also hinder NPB-PARPi efficacy through an elevated capacity for resistance to PARPis." (PMID 35725817, 2022).
metabolic disease (1 paper, 2017). A congenital disorder (due to inherited enzyme abnormality) or acquired (due to failure of a metabolically important organ) disorder resulting from an abnormal metabolic process. "The specificity of LysoSLs was evaluated by testing plasma from GD, infantile KD and NPB carriers, and patients affected with other metabolic diseases." (PMID 28749998, 2017).
NPB also shares sentences with these, for which no sentence is quoted: peripheral neuropathy (2 papers); breast carcinoma (1); influenza (1); Onset (1); tumour (1); type 2 diabetes (1).